PIK3R1 (phosphoinositide-3-kinase regulatory subunit 1)
Diseases named in the same sentence as PIK3R1 in open-access papers (continued):
Sharing a sentence is not in itself a finding about the gene and the disease.
liver fibrosis (6 papers, 2015 to 2025). "A previous study showed that direct targeting of PIK3R1 in hepatic stellate cells inhibits liver fibrosis, indicating that PIK3R1 is probably participating in hernia-associated fibrosis." (PMID 31910207, 2020). "To characterize the effect of PIK3R1 or AKT3 on liver fibrosis, we knockdown PIK3R1 or AKT3 expression in LX1 cells by siRNA transfection." (PMID 25356754, 2015). "A PPI network showed that as hub and core targets, SRC, PIK3R1, STAT3 and AKT1 were potential anti-liver fibrosis targets of RGGs." (PMID 35115923, 2021). "Meanwhile, much evidence has confirmed that PIK3R1, STAT3 and AKT1 can regulate crucial cellular processes, including proliferation, survival, growth, autophagy, and metabolism, and improve liver fibrosis." (PMID 35115923, 2021). "In contrast, CCl4-treated mice supplemented with miR-29b showed significant reduced expression of PIK3R1, total AKT3 and p-AKT, which paralleled the improvement in histological severity of liver fibrosis." (PMID 25356754, 2015). "Among the miRNAs predicted to target genes, we revealed for the first time that PIK3R1 and AKT3 act as critical effectors of miR-29b in liver fibrosis." (PMID 25356754, 2015). "Hence, we thought that RGGs presented anti-liver fibrosis activity by regulating the expression of SRC, PIK3R1, STAT3, AKT1 and other core targets." (PMID 35115923, 2021). "In particular, we demonstrated by a variety of in vitro and in vivo approaches that phosphoinositide-3-kinase regulatory subunit 1 (PIK3R1) and protein kinase B (AKT3) are direct targets of miR-29b in HSCs responsible for signaling onset of HSCs activation and liver fibrosis." (PMID 25356754, 2015).
lung adenocarcinoma (6 papers, 2015 to 2025). A carcinoma that arises from the lung and is characterized by the presence of malignant glandular epithelial cells. "Further investigation revealed which we were pleasantly surprised to find that both SPP1 and PIK3R1 were associated with lung adenocarcinoma prognoses and immunotherapy." (PMID 36688087, 2023). "We also found in lung adenocarcinoma that the overexpression of PIK3R1 was associated with miR-21-5p and the low expression of miR-21-5p means good prognosis." (PMID 36688087, 2023). "It has been found that lung adenocarcinoma exhibits high expression of SPP1 and that this has been associated with poor prognosis, while low expression of PECAM1 and PIK3R1 is associated with poor prognosis (P < 0.05)." (PMID 36688087, 2023). "Here, we analyzed PIK3R1 through the UALCAN website and found that PIK3R1 was highly expressed in lung adenocarcinoma compared with normal lung tissue." (PMID 36688087, 2023). "SPP1 is highly expressed in lung adenocarcinoma compared with normal lung tissue, and the high expression of SPP1 is associated with poor prognosis, while the high expression of PECAM1 and PIK3R1 is associated with good prognosis." (PMID 36688087, 2023). "Apart from two microRNA, miR-21-5p and miR-146a-5p are related to the prognosis of lung adenocarcinoma which are consistent to PIK3R1 and SPP1." (PMID 36688087, 2023). "We reveal two potential biomarkers for lung adenocarcinoma, including PIK3R1 and SPP1." (PMID 36688087, 2023). "We demonstrated that SPP1 and PIK3R1 were possible biomarkers of lung adenocarcinoma." (PMID 36688087, 2023). "Surprisingly, the survival analysis revealed that three genes (PIK3R1, SPP1, and PECAM1) have a clear correlation with OS in lung adenocarcinoma patients." (PMID 36688087, 2023). "Three genes (PIK3R1, SPP1, and PECAM1) have a clear correlation with OS in lung adenocarcinoma patients." (PMID 36688087, 2023). "The survival curve indicated that the expression of PIK3R1, PIK3CA, and AKT1 correlated with the mOS of lung adenocarcinoma (p < 0.05)." (PMID 36654811, 2023). "We found three genes (PIK3R1, SPP1, and PECAM1) that have a clear correlation with OS in the lung adenocarcinoma patient." (PMID 36688087, 2023). "The PI3K protein family acted as critical roles in the lung adenocarcinoma, since the components of the PI3K protein family include PIK3C2B, PIK3CA, PIK3R1 and so forth were presented in the intersections." (PMID 28503373, 2017).
neuroblastoma (6 papers, 2013 to 2025). Neuroblastoma (NB) is the most common solid, extracranial childhood tumor. "The mRNA of PIK3R1 and p85α, p55α, and p50α isoforms encoded by PIK3R1 are significantly higher expressed in stage 1-2 neuroblastoma than in stage 4 neuroblastoma." (PMID 41189817, 2025). "The two shorter proteins isoforms p55α and p50α encoded by PIK3R1 were detected at significantly lower levels in stage 4 compared to stage 1–2 neuroblastomas, p < 0.001 and p < 0.05 respectively." (PMID 23597230, 2013).
renal cell carcinoma (6 papers, 2015 to 2022). "The repression of PIK3R1 by miR-486-5p is also described in renal cell carcinoma and leads to a reduction in tumor aggressiveness." (PMID 35337095, 2022). "Moreover, the PAK1 and PIK3R1 genes have a crucial role in cell migration and mobility in the KEGG renal cell carcinoma pathway, and both of them have been extracted by our pipeline as KIRC IC genes." (PMID 33712625, 2021).
viral infections (6 papers, 2018 to 2022). "PI3K signaling in NK cells and mutations in PIK3R1 have been linked with human immunodeficiency and viral infections." (PMID 33765435, 2021). "CD4 T cell numbers were reduced in 32% of patients and NK cell numbers were reduced in 11% of patients with severe virus infections and PIK3R1 mutations." (PMID 29599765, 2018). "Viral infections in patients with germline gain-of-function mutations in PIK3R1." (PMID 29599765, 2018). "Hence, the miR-455-3p-PIK3R1 axis is thought to likely participate in the progression of virus infection." (PMID 35864512, 2022). "Meanwhile, previous studies have been confirmed that PIK3R1 have been identified to be differentially expressed in many human cancers and implicated in tumor progression and metastasis, but PIK3R1 is increasingly being nominated as a pivotal mediator in the viral infections in recent years." (PMID 35864512, 2022).
astrocytoma (5 papers, 2007 to 2025). "WHO Grade 4 astrocytoma patients with PIK3R1 mutations are expected to benefit from PI3K inhibitors." (PMID 37667984, 2023). "We also found that alterations in PIK3R1, Notch1, and Mycn are associated with the overall survival of molecular WHO Grade 4 astrocytoma." (PMID 38970209, 2024). "Meanwhile, other molecular biomarkers indicating worse outcome in IDH‐mutant astrocytoma, including NOTCH1 mutations and incomplete resections in oligocytoma and PIK3R1 mutations, RB1 mutations and CDK4 mutations and amplifications in astrocytoma." (PMID 37667984, 2023). "A more recent study reported that PIK3R1 is uniquely overexpressed in IDH1-mutant grade 4 astrocytoma, indicating that combined targeting of the PI3K/AKT/mTOR pathway and the immune system may be necessary for effective treatment in this subtype." (PMID 40504311, 2025). "The results of univariate regression analysis suggested that alterations in PIK3R1 (p = 0.033), Notch1 (p = 0.027), and Mycn (p = 0.027) may be associated with shorter OS in molecular WHO Grade 4 astrocytoma." (PMID 37667984, 2023). "Variations of BCOR, MYCN, NOTCH1, and PIK3R1 and positive immunohistochemistry for S100 showed statistically significant results in univariate survival analysis in WHO grade 4 astrocytoma." (PMID 38970209, 2024). "PIK3R1, Notch1, and Mycn alterations might affect the overall survival of molecular WHO Grade 4 astrocytomas." (PMID 37667984, 2023). "The finding of PIK3R1, Notch1, and Mycn alterations as negative prognostic factors in molecular WHO Grade 4 astrocytomas may shed light on understanding the biobehavioral progression and also potential targeted therapies for this specific subset of astrocytomas." (PMID 37667984, 2023).
breast tumors (5 papers, 2013 to 2025). "PI3K/AKT signaling system is substantially active in carcinogenesis; PIK3CA, PIK3R1, PTEN, AKT, and other genes have high-frequency mutations (PIK3CA gene is mutated in around 36% of breast tumors)." (PMID 36937843, 2023). "The expression and activity of SRC or PIK3R1 are highly upregulated in malignant breast tumor tissues and have been correlated with decreased survival of BC patients." (PMID 33628298, 2021). "GRB2 interaction with LAT and LAX1 observed in breast tumor cells may be an indirect interaction through PLCG1, VAV or PIK3R1." (PMID 23826330, 2013).
endometrioid carcinoma (5 papers, 2014 to 2022). "PIK3R1 has also been linked to epithelial neoplasia and cancer, endometrial ovarian cancer, and endometrioid carcinoma." (PMID 24774302, 2014). "Endometrioid carcinomas, which originate from the same tissue as OCCC, have been shown to frequently harbor mutations in genes such as CTNNB1 (42% of samples), KMT2D (31%), KMT2B (19%), and PIK3R1 (19%)." (PMID 33153119, 2020).
Hyperglycemia (5 papers, 2016 to 2022). An increased concentration of glucose in the blood. "Altogether, these findings suggest that Pik3r1 downregulation promotes hyperglycaemia by impairing GLUT4-facilitated glucose uptake." (PMID 27199286, 2016). "SNP rs10515074 in PIK3R1, a gene encoding the 85 kD regulatory subunit of phosphatidylinositol 3-kinase enzyme, which is an upstream member that triggers thePI3K/AKT/mTOR signaling pathway, was associated with hyperglycemia and leucopenia." (PMID 28727815, 2017). "ABCB1 rs1045642 was associated with risk of mucositis (P = 0.031), while PIK3R1 rs10515074 and RAPTOR rs9906827 were associated with hyperglycemia and non-infectious pneumonitis (P = 0.016 and 0.024, respectively)." (PMID 28727815, 2017).
Hypertension (5 papers, 2023 to 2026). The presence of chronic increased pressure in the systemic arterial system. "In a heterozygous disadvantage model, we found previously that longevity-associated PIK3R1 genotype protects against mortality risk from having at least one of the cardiovascular conditions of hypertension, CHD and stroke." (PMID 37178326, 2023). "Besides, longevity-promoting resilience genes like FLT1, Foxo3, GHR3, MAP3K5, PIK3R1 could mitigate mortality from hypertension, which further indicating the genetic influences in hypertension and vascular aging." (PMID 41507140, 2026). "In studies of FOXO3, MAP3K5, PIK3R1, GHR, and FLT1 we found that for each, the genetic variants associated with longer lifespan may activate cell resilience mechanisms, leading to amelioration of the adverse effects of hypertension." (PMID 37561089, 2023).
sarcoma (5 papers, 2007 to 2025). A usually aggressive malignant neoplasm of the soft tissue or bone. "In addition, reference transcriptomic data from the TCGA database revealed a markedly elevated expression of PIK3R1 in sarcoma (SARC) tissues relative to normal controls, supporting a potential role of PI3K pathway dysregulation in tumorigenesis." (PMID 41471362, 2025). "We analysed the expression of PIK3R1 in human different sarcomas using Oncomine database." (PMID 34741385, 2021). "The pan‐cancer analysis from encori database found that there was highly negative correlation between miR‐21‐5p and PIK3R1 in sarcoma (Person r = −0.443, P = 5.31E‐14; y = −0.4503X + 10.7515)." (PMID 34741385, 2021).
Stroke (5 papers, 2021 to 2023). Sudden impairment of blood flow to a part of the brain due to occlusion or rupture of an artery to the brain. "In the process of stroke, PIK3CA and PIK3R1 are the main genes that promote cell survival and reduce cell apoptosis." (PMID 38013375, 2023). "Accumulating evidence has confirmed that, under the injuries of stroke, cerebral ischemia, and I/R and activation of PI3K/Akt or PI3K/Akt/mTOR signaling pathway, PIK3CA, PIK3R1, AKT1, MAPK1, MAPK3 are main genes that play important roles in promoting cell survival and reducing cellular apoptosis." (PMID 35432563, 2022).
acute myeloid leukemia (4 papers, 2010 to 2025). Acute myeloid leukemia (AML) is a group of neoplasms arising from precursor cells committed to the myeloid cell-line differentiation. "Erianin inhibited the transcriptional level of PIK3R1 by enhancing the protein level of PPAR, thereby suppressing the PI3K/AKT pathway, which resulted in the suppression of acute myeloid leukemia." (PMID 40267096, 2025).
breast invasive carcinoma (4 papers, 2016 to 2025). "Furthermore, the expression of both PIK3R1 and PIK3R2 was associated with the level of immune infiltration in multiple tumors, such as breast invasive carcinoma." (PMID 35395865, 2022).
endometriosis (4 papers, 2019 to 2024). The growth of functional endometrial tissue in anatomic sites outside the uterine body. "A previous study involving bioinformatics-based analysis of the genes associated with endometriosis reported the involvement of PIK3R1 as a potential driver of the disease." (PMID 39598271, 2024). "Potential oncogenic mutations found included PIK3CA, KRAS, PIK3R1, and FGFR2 in benign epithelial endometrium from women with uterine fibroids, and ARID1A mutations in endometrial stroma from women with endometriosis." (PMID 31717878, 2019). "The identification of AKT1, or more generally, genes in the PI3K/AKT/mTOR pathway (including MTOR, PIK3CA, and PIK3R1 in addition to ATK1), is in line with current interests targeting this pathway in endometriosis." (PMID 35401535, 2022). "Additionally, our study highlights several potential key genes likely involved in the pathogenesis of endometriosis by altering cell migration, such as DKK1, GRB7, MIEN1, PIK3R1, and KRT19." (PMID 39595577, 2024).
Glucose intolerance (4 papers, 2016 to 2021). Glucose intolerance (GI) can be defined as dysglycemia that comprises both prediabetes and diabetes. "Here, we found that dietary vitamin D supplementation upregulated Pik3r1 in an animal model of antipsychotic-induced glucose intolerance." (PMID 27199286, 2016). "Inhibition of class IA PI3K via knockout of pik3r1 and pik3r2 genes in mice led to a decrease in insulin secretion and increased glucose intolerance, suggesting that class IA PI3K in β-cells is important for maintaining intracellular Ca2+ levels and cell-cell synchronization." (PMID 28856166, 2017). "For example, mice with liver-specific KO of Pik3r1 demonstrate improved glucose tolerance and insulin-stimulated glucose uptake in skeletal muscle and are protected against HFD-induced glucose intolerance." (PMID 29997524, 2018).
ischemic stroke (4 papers, 2018 to 2022). A stroke disorder caused by obstruction of blood flow to the brain, due to thrombotic (local blood clot formation) or embolic (due to a blood clot or other material traveling from another site) event. "Notably, MAPK3, MAPK1, HSP90AA1, STAT3, PIK3R1, PIK3CA, and AKT1 were the main target proteins involved in the pathogenesis of ischemic stroke with Qi deficiency and blood stasis syndrome." (PMID 35401166, 2022).
lymphoma (4 papers, 2017 to 2022). A malignant (clonal) proliferation of B- lymphocytes or T- lymphocytes which involves the lymph nodes, bone marrow and/or extranodal sites. "We describe a new dominant PIK3R1 mutation causing APDS2 presenting with lymphoma and systemic refractory autoimmunity." (PMID 34307262, 2021). "PIK3R1 is altered in 3.62% of solid cancer patients and 1.52% of lymphoma patients." (PMID 35990641, 2022).
meningioma (4 papers, 2012 to 2023). A generally slow growing tumor attached to the dura mater. "CREBBP, PIK3CA (R108H), PIK3R1, BRCA1, and SMARCB1 are the most represented mutations; unfortunately, none of these mutations can predict the rate of recurrence in NF2-mutated meningiomas." (PMID 35892898, 2022). "We observed that both PI3K (PIK3R1, PIK3R3) and Akt (AKT3) genes were up-regulated in fibroblastic meningioma, and total Akt and phosphorylation Akt were also overexpressed in tumor tissues." (PMID 23285163, 2012).
ovarian tumors (4 papers, 2010 to 2025). "However, opposite results of PIK3R1 and p85α overexpression have also been reported in ovarian tumors." (PMID 39858051, 2025).
serous ovarian cancer (4 papers, 2012 to 2025). "In contrast to mutations, PIK3R1 copy number loss is frequently observed in high-grade serous ovarian cancers (HGSOCs) (68%) and is correlated with reduced PIK3R1 mRNA expression." (PMID 39858051, 2025). "Additionally, it was shown that serous ovarian cancer cell lines with PIK3R1 loss demonstrated multiple tumorigenic properties like increased proliferation, migration, and invasion." (PMID 39858051, 2025). "PIK3R1 copy number loss was the most frequent in serous ovarian cancer across TCGA15,16." (PMID 30755611, 2019). "A detailed analysis of the PIK3R1 copy number in serous ovarian cancer across TCGA revealed 68.4% heterozygous and 3.5% homozygous loss, respectively." (PMID 39858051, 2025). "Similarly, a study on serous ovarian cancer cell lines demonstrated that PIK3R1 downregulation induced the expression of antiapoptotic BCL2, as well as genes involved in cell cycle progression (CCNB1) and metastasis (MMP9 and VEGFA)." (PMID 39858051, 2025). "Decreased expression of PIK3R1 was also observed in serous ovarian cancers in TCGA cohorts and, in agreement with our results, was correlated with the gene copy numbers, suggesting that reduced expression may be related to gene allele loss." (PMID 39858051, 2025). "We then assessed the functional consequence of p85α downregulation in serous ovarian cancer cell lines (SKOV3, OVCAR8, and OAW28), which express high level of p85α and carry a wild-type PIK3R1 gene." (PMID 30755611, 2019).
thyroid cancer (4 papers, 2021 to 2025). "Based on the TIMER platform, PIK3R1 has the strongest association with thyroid carcinoma, and notably, YWHAZ also correlated strongly with thyroid carcinoma in immune cell infiltration." (PMID 39403688, 2025). "Further exploration of the consistently modulated genes, particularly FN1, PIK3R1, and TGFBR1, may reveal new molecular insights and therapeutic targets for managing aggressive thyroid cancers." (PMID 40650218, 2025). "PIK3R1 RNA could be moderately expressed in the thyroid by regulating the PI3K-Akt signal pathway, which plays an important role in the development of thyroid cancer." (PMID 34840968, 2021).